GALNT18 (polypeptide N-acetylgalactosaminyltransferase 18)
Description:
Catalyzes the initial reaction in O-linked oligosaccharide biosynthesis, the transfer of an N-acetyl-D-galactosamine (GalNAc) residue from UDP-GalNAc to a serine or threonine residue on the protein receptor.
Synonyms: GalNAc-T18; GALNTL4; MGC71806; GALNT15; GALNACT18; GalNAc-T15
Tractability: Antibody: UniProt predicts a signal peptide or a membrane-spanning region. PROTAC: ubiquitination databases record sites on it.
Gene: Protein-coding gene on chromosome 11 (11,270,864 to 11,622,431, reverse strand). Ensembl gene ENSG00000110328.
Subcellular location: Golgi apparatus membrane
Subcellular location (Human Protein Atlas): Golgi apparatus; Cytosol; Vesicles
Pathways (Reactome):
Metabolism of proteins: O-linked glycosylation of mucins
Gene Ontology:
Molecular function: polypeptide N-acetylgalactosaminyltransferase activity
Biological process: protein O-linked glycosylation via N-acetyl-galactosamine; protein O-linked glycosylation
Cellular component: Golgi apparatus; Golgi membrane
Genetic constraint (gnomAD): Loss-of-function variants: 42 observed, 63.37 expected, observed/expected ratio (o/e) 0.66, 90% interval 0.52 to 0.86. The upper end of that interval is the gene's LOEUF score, 0.86, which puts it in group 3 of 6, group 1 being the genes least tolerant of losing a copy. Missense variants: 698 observed, 786.3 expected, observed/expected ratio (o/e) 0.89, 90% interval 0.83 to 0.94. Synonymous variants: 358 observed, 313.88 expected, observed/expected ratio (o/e) 1.14, 90% interval 1.04 to 1.25.
Homologues: Orthologues: chimpanzee GALNT18 (100% identical), pig GALNT18 (99% identical), guinea pig GALNT18 (99% identical), dog GALNT18 (99% identical), mouse Galnt18 (99% identical), rat Galnt18 (98% identical), rabbit GALNT18 (95% identical), macaque GALNT18 (94% identical), zebrafish galnt18b (81% identical), tropical clawed frog galnt18 (79% identical), zebrafish galnt18a (74% identical), Caenorhabditis elegans gly-3 (29% identical), and 3 more. Paralogues in human: GALNT9 (50% identical), GALNT17 (49% identical), GALNT8 (46% identical), GALNT6 (31% identical), GALNT2 (31% identical), GALNT1 (31% identical), GALNT13 (30% identical), GALNT3 (30% identical), GALNT11 (30% identical), GALNT4 (29% identical), GALNT12 (29% identical), GALNT5 (29% identical), and 7 more.
Diseases named in the same sentence as GALNT18 in open-access papers:
GALNT18 is named in the same sentence as 20 diseases in open-access papers, as found by Europe PMC text mining. Sharing a sentence is not in itself a finding about the gene and the disease. The quoted sentences say what the papers report.
lupus (2 papers, 2020 to 2023). "A longitudinal analysis in lupus patients showed that the demethylation of GALNT18 was associated with the development of active lupus nephritis." (PMID 36693108, 2023).
lupus nephritis (2 papers, 2020 to 2023). Glomerulonephritis in the context of systemic lupus erythematosus. "Importantly, demethylation of a CpG site located within GALNT18 was associated with the development of active lupus nephritis." (PMID 33108347, 2020).
COVID-19 (1 paper, 2021). A disease caused by infection with severe acute respiratory syndrome coronavirus 2. "Finally, the AncestryDNA COVID-19 host genetic study identified COVID-19 genetic associations with SLC6A20, LZTFL1 variants on the chromosome, ABO locus on chromosome 9 and a novel association on chromosome 11 that includes Polypeptide N-Acetylgalactosaminyltransferase 18 (GALNT18)." (PMID 34575070, 2021).
tumor (4 papers, 2013 to 2024). "GALNT10 and GALNT18 are members of the GalNAc polypeptide N‐acetyl‐galactosaminyltransferases, which catalyse O‐linked glycosylation of mucin and can promote EGFR O‐glycosylation and subsequent AKT phosphorylation, leading to tumour proliferation." (PMID 38279874, 2024).
GALNT18 also shares sentences with these, for which no sentence is quoted: thyroid cancer (2 papers); bacterial infection (1); bladder urothelial carcinoma (1); cancer (1); colon adenocarcinoma (1); cutaneous melanoma (1); Hypertension (1); Larsen syndrome (1); lung carcinoma (1); melanoma (1); nephritis (1); neurodegenerative disease (1); neurological disorders (1); Obesity (1); pancreatic cancer (1); stomach adenocarcinoma (1).